NFE2L2 (NFE2 like bZIP transcription factor 2)
Diseases named in the same sentence as NFE2L2 in open-access papers (continued):
Sharing a sentence is not in itself a finding about the gene and the disease.
infection (35 papers, 2010 to 2025). The state of being infected such as from the introduction of a foreign agent such as serum, vaccine, antigenic substance or organism. "Among the downregulated genes in Mb04-303 infections, the NFE2L2 gene encodes a major transcription factor that responds to oxidative stress and inflammation through the induction of various antioxidant response elements." (PMID 37764968, 2023). "While we did not observe a statistically significant effect, knock-out of NFE2L2 showed a trend toward enhanced infection, whereas knock-out of the endogenous inhibitor KEAP1 strongly decreased infection." (PMID 38319076, 2024). "In line with the NFE2L2 downregulation, Mb04-303 infections upregulated the expression of PSMB2, PSMB3, PSMA2, PSMD2, PSMD8, PSMB6 and PSMB9." (PMID 37764968, 2023). "In this regard, we observed that infection with Mtb activates anti-oxidative response by triggering the expression of principal transcription activator of antioxidant genes, NRF2 (encoded by Nfe2l2) that then leads to the expression of its target genes." (PMID 37871034, 2023). "At 1.5 h, the transcriptome of IECs showed the induction of nuclear factor, erythroid 2 like 2 (nfe2l2) together with superoxide dismutase (sod2); their RNA levels peaked at 3 h of infection." (PMID 30062089, 2018). "Within this pathway, NFE2L2, which encodes a proteasome-regulated transcriptional factor involved in antioxidant genes, was downregulated, while the genes encoding the proteasome components PSMB2, PSMB3, PSMA2, PSMD2, PSMD8, PSMB6 and PSMB9 were upregulated in Mb04-303 infections." (PMID 37764968, 2023). "There is emerging interest in the role of nuclear factor erythroid 2-related factor 2 (NFE2L2)/Nrf2, a master regulator of antioxidant and anti-apoptosis system, in the regulation of mitochondrial homeostatic functions in a variety of physiological and pathological conditions including infection." (PMID 32922385, 2020). "Other inducers include hypoxia through HIF1A/HIF-1α, oxidative stress via NFE2L2/NRF2 activation, protein misfolding, and infection through pattern recognition receptors (PRRs)." (PMID 40910070, 2025). "NFE2L2 (Nuclear Factor Erythroid 2-Like 2; OMIM 600492), ZNF250 (Zinc Finger Protein 250) and ZNF549 (Zinc Finger Protein 549) were activated in response to infection (i.e., Herpes Simplex Virus) and inflammation." (PMID 33466592, 2021). "Consistent with a central role for oxidative stress responses in cell-intrinsic responses to infection, key antioxidant enzymes (GSR, CAT, GPX1, and PRDX1) were downregulated by YFV-17D and select genes (SOD2, NFE2L2, and KEAP1) were upregulated by MnTBAP treatment." (PMID 39282299, 2024). "However, we observed a trend toward enhanced HCov-229E infection relative to cell viability which is in line with the notion that the activators of AHR and NFE2L2 were antiviral." (PMID 38319076, 2024). "During inflammation and infection, Irg1/Itaconate pathway has been shown to control myeloid cell function through multiple mechanisms, such as succinate dehydrogenase (SDH) inhibition, nuclear factor erythroid 2-like 2 (NFE2L2 or NRF2) activation, and modulation of oxidative stress." (PMID 39499730, 2024). "Expression of Nrf2 (Nfe2l2) in the lungs was induced by MAC infection in wild-type mice, although it was not induced by infection in Nrf2−/−mice." (PMID 33563837, 2021).
neurodegenerative disease (26 papers, 2016 to 2025). A disorder of the central nervous system characterized by gradual and progressive loss of neural tissue and neurologic function. "NFE2L2 plays a vital role in the treatment of neurodegenerative diseases and regulation of ferroptosis." (PMID 34869576, 2021). "The nuclear factor E2 related factor 2 (Nrf2/NFE2L2) has been proved to play a key role in neurodegenerative disease treatment and ferroptosis regulation." (PMID 32372896, 2020). "It is well-known that the nuclear factor E2 related factor 2 (NRF2/NFE2L2) plays a key role in neurodegenerative disease and ferroptosis regulation." (PMID 33167414, 2020). "Impairment of the NFE2L2 signaling pathway and mitochondrial dysfunction is evident in the pathogenesis of degenerative diseases, yet the development of drugs that exploit the targeting of mitochondria through the activation of NFE2L2 is only in its infancy." (PMID 31057691, 2019). "Previous studies indicated that transcription factor NFE2L2 controls antioxidant response element (ARE)-regulated antioxidant genes, contributing to an essential protective role in the brains against neurodegenerative diseases." (PMID 26887053, 2016).
cardiovascular diseases (14 papers, 2018 to 2024). "Interestingly, as reviewed in detail by Chen and Maltagliati, several functional Nfe2l2 polymorphisms are associated with risk of human cardiovascular disorders, for example, rs6721961 is a C-to-A transversion at −650 nt location and results in diminished ARE activity in the Nfe2l2 gene promoter." (PMID 35204118, 2022). "We constructed an mRNA–miRNA–lincRNA ceRNA interaction network centered on miR-22-3p and used the starBase v2.0 and miRWalk databases to predict eight related transcription factors associated with cardiovascular disease, namely, CTCF, JUN, JUND, NFATC1, NFE2L2, RAD21, RELA, and TAL1." (PMID 36105099, 2022).
kidney disease (12 papers, 2016 to 2024). "INPP5B impairment has been associated with severe renal phenotypes, such as proximal-tubule endocytosis, and targeting NFE2L2 (NRF2) has been tested as a method of preventing kidney disease progression." (PMID 32386536, 2020).
adenocarcinoma (11 papers, 2012 to 2024). A common cancer characterized by the presence of malignant glandular cells. "The other genes that were much more mutated in SCC (with estimated mutation proportion in SCC and in adenocarcinoma, respectively) were LRP1B (23%, 10%), KMT2D (16%, 7%), FAT1 (15%, 5%), CDKN2A (12%, 2%), NOTCH1 (10%, 3%), and NFE2L2 (10% and 1%)." (PMID 34645806, 2021). "This analysis revealed that the Nfe2l2 pathway involved in cellular response to oxidizing insults was enriched most highly in all 4 high TrkB-T1 expresser SCCs tested, LASC, OSCC, ESSC and LUSC, and not in the high TrkB-T1 adenocarcinomas." (PMID 31221127, 2019).
neurological disorders (11 papers, 2009 to 2024). "Several research studies on nitrosative/oxidative stress or inflammatory response in neurological diseases have suggested the critical role of the antioxidant pathway involving the Kelch-like ECH-associated protein (Keap1)/nuclear factor erythroid 2-like 2 (NFE2L2, namely Nrf2)." (PMID 34122094, 2021).
metabolic disease (9 papers, 2014 to 2023). A congenital disorder (due to inherited enzyme abnormality) or acquired (due to failure of a metabolically important organ) disorder resulting from an abnormal metabolic process. "Furthermore, NFE2L2 dysfunction may lead to functional impairment of arteries, increasing susceptibility of blood vessels to injury in metabolic diseases." (PMID 24790085, 2014).
retinopathy (5 papers, 2016 to 2024). "Reduced RCBTB1 expression in patient‐derived iPSC‐RPE was accompanied by reduced expression of oxidative stress response genes activated by NFE2L2, supporting previous observations made in PBMCs derived from patients with RCBTB1‐associated retinopathy." (PMID 34617687, 2021).
gastrointestinal tumours (1 paper, 2018).
hematological cancers (1 paper, 2025). "Focusing on the NRF2 transcription factor (TF), the genetic variants on the NFE2L2 gene that codify this TF have been described as associated with the development and progression of various solid and hematological cancers." (PMID 40565143, 2025).
NFE2L2 also shares sentences with these, for which no sentence is quoted: Cerebral ischemia (11 papers); chronic kidney disease (11); renal fibrosis (10); asthma (9); ischemic stroke (8); osteoporosis (8); inflammatory bowel disease (7); myocardial ischemia (6); non-alcoholic steatohepatitis (6); cognitive decline (5); heart failure (5); intracerebral hemorrhage (5); myocardial infarction (5); Anxiety (4); renal cell carcinoma (4); age (3); age-related macular degeneration (3); autism (3); cardiomyopathy (3); chronic obstructive pulmonary disease (3); fibrosarcoma (3); Friedreich ataxia (3); gastric ulcer (3); glaucoma (3); glomerulosclerosis (3); Hepatitis (3); Huntington disease (3); hypothyroidism (3); inflammation (3); lupus nephritis (3).
A further 177 diseases each share a sentence with NFE2L2 in 3 papers or fewer.